BRCA1 (BRCA1 DNA repair associated)
Diseases named in the same sentence as BRCA1 in open-access papers (continued):
Sharing a sentence is not in itself a finding about the gene and the disease.
breast tumors (continued). "Patients presenting with breast tumor histology of other than invasive ductal carcinoma showed a 73 % decreased risk of BRCA1 mutations (RP = 0.27; 95 % CI 0.08–0.89; P = 0.03)." (PMID 27553291, 2016). "HCC1937 cells that are derived from a homozygous BRCA1 deficient breast tumor, express a truncated and unstable form of BRCA1 and are hypersensitive to DNA damaging agents." (PMID 26745677, 2016). "An array CGH based classifiers recognizing this genomic pattern of BRCA1-mutated breast tumors was identified." (PMID 27935989, 2016). "In the current study, we applied an in-depth proteomic profiling of secretomes and extracellular vesicles (EVs) of BRCA1 -deficient and -proficient breast tumor cell lines derived from three validated GEMMs." (PMID 27566577, 2016). "Given that WNT4 upregulation activates WNT signaling, this suggests that activated WNT signaling potentially mediates the effect of WNT4 on promoting BCSC generation in BRCA1-deficient breast tumors." (PMID 27556296, 2016). "To reveal the functional role of miR-129-5p in the BRCA1-deficiency-induced malignant phenotypes of breast tumor cells, we performed a miR-129-5p rescue study by co-transfecting the miR-129-5p mimic with BRCA1 siRNA into MCF10DCIS cells." (PMID 27556296, 2016). "A recent comprehensive analysis of The Cancer Genome Atlas (TCGA) program showed that around twenty percent of basal-like breast tumors have an inherited or somatic BRCA1 or BRCA2 nucleic acid variant." (PMID 26848770, 2016). "First, by applying the RIPSs, we were able to discriminate with fairly high accuracy breast tumors containing germline BRCA1 or BRCA2 mutations from those that occurred sporadically." (PMID 27788678, 2016). "Over 75% of breast tumors found in women with a BRCA1 mutation have a so-called triple negative phenotype (TNBC), meaning that these tumors do not express estrogen receptor, progesterone receptor and human epidermal growth factor receptor type 2 (HER2)." (PMID 28164176, 2016). "Future studies are warranted to assess the non-invasive diagnostic power of these proteins for early detection of breast tumors in cohorts of BRCA1 mutation carriers." (PMID 27566577, 2016). "Specifically, emerging evidence points to the luminal progenitor population as the cell of origin of BRCA1-associated breast tumours." (PMID 27893411, 2016). "In BRCA1 mutation carriers, breast tumor samples have a characteristic pattern of DNA gains and losses." (PMID 27935989, 2016). "It is well known that most of the breast tumours arising in female BRCA1 mutation carriers tend to be ER− and PR−, with a small percentage being ER+." (PMID 26857456, 2016). "Unexpectedly, in breast tumor tissues carrying inherited BRCA1 mutations, insertion/deletion somatic mutations were found in the vicinity of BRCA1-bound gene termination sites where BRCA1 normally engages in the repair of R-loop-associated DNA damage." (PMID 25699710, 2015). "The triple-negative (TN) morphology of breast tumor is found in the 57% of patients with the BRCA1 gene mutations and 23% of patients with the BRCA2 gene mutations." (PMID 25705321, 2015). "For example, breast tumors and ovary tumors have common risk factors including hormone therapy, obesity, and inherited genetic risk such as BRCA1 and BRCA2." (PMID 26273658, 2015). "Strikingly, within some of these genes in BRCA1 null breast tumors, there are specific insertion/deletion mutations located close to R-loop-mediated BRCA1 binding sites within TRs." (PMID 25699710, 2015). "Our previous study reported increased levels of both angiopoietin-1/-2 and VEGF in BRCA-related breast tumors, highlighting their contribution to vascular remodeling in patients harboring BRCA1/2 mutations." (PMID 25333258, 2015). "In the present case report we considered HER2-positive breast tumor occurred in the BRCA1 germline mutated context." (PMID 26426992, 2015).
breast tumors (continued). "We identified 114 breast tumors, of which 71 (62.3 %) were BRCA1-associated and 43 (37.7 %) were BRCA2-associated." (PMID 26496879, 2015). "Previous studies documented a high degree (~75 %) of correlation between loss of BRCA-1 and reduced ERα expression in human breast tumors." (PMID 26715507, 2015). "Next, we wished to explore if differential expression of AhR and BRCA-1 promoter CpG methylation associated with pathological classification of human breast tumor subtypes based on receptor status." (PMID 26715507, 2015). "The majority of breast tumors, especially TNBCs express high levels of BRCA1-IRIS associated with increased p-AKT and survivin expression, and lack of BRCA1 expression." (PMID 25583261, 2015). "Breast tumors carrying BRCA1 mutations are considered to be sensitive to inhibitors of poly (ADP-ribose) polymerases (PARPs) that are nuclear enzymes implicated in cellular responses to DNA injury provoked by genotoxic stress." (PMID 24970653, 2014). "The breast tumor phenotype of female BRCA2 female mutation carriers is less distinctive than that of BRCA1 mutation carriers." (PMID 25857409, 2014). "One of the mechanisms triggering CUL4A overexpression is the 13q34 amplification and this genomic aberration has been shown to be associated with breast tumors characterized by exhibiting BRCA1 impairment or a basal-like phenotype." (PMID 24870930, 2014). "Regulation of AKT by BRCA1 in both our cell model and BRCA1-mutated breast tumors was suggested to participate in the effect of BRCA1 on glycolysis." (PMID 25010005, 2014). "In one study, two out of 48 non-BRCA1/2 breast tumors exhibited chromosomal aberration patterns similar to those found in BRCA1-mutated tumors, of which hypermethylation of the BRCA1 promoter was demonstrated in one sample." (PMID 24479546, 2014). "This study has re-estimated the likelihood of BRCA1 or BRCA2 mutation status associated with breast tumor features commonly measured in the clinical setting, by analyzing much larger datasets than previously used for this purpose." (PMID 25857409, 2014). "The distribution of histopathological features of invasive breast tumors in BRCA1 or BRCA2 germline mutation carriers differs from that of individuals with no known mutation." (PMID 25857409, 2014). "Another critical point concerns the resistance to camptothecin (CPT) of some BRCA1-deficient breast tumours." (PMID 23805307, 2013). "In this study, we provide the first pathological, immunohistochemical and molecular characterization of a breast tumor of the ACC type developed in a BRCA1 mutation carrier." (PMID 23374397, 2013). "We found that breast tumors from BRCA1 and BRCA2 mutation carriers display characteristic RNA expression patterns, allowing them to be distinguished from sporadic tumors." (PMID 23704984, 2013). "Breast tumors arising from BRCA1 mutation acquired distinct pathological and gene expression profiles." (PMID 23405268, 2013). "In the present study, frozen, primary breast tumors were collected from BRCA1 (n = 33) and BRCA2 (n = 22) mutation carriers and from sporadic cases (n = 128)." (PMID 23704984, 2013). "It thus appears important to simultaneously evaluate 53BP1 status and BRCA1 mutation/promoter methylation to precisely estimate homologous recombination functionality in breast tumours." (PMID 24191908, 2013). "The vast majority of breast tumors developing in BRCA1 carriers shows inactivation of the wild-type allele by either somatic genetic (mutations or loss of heterozygosity (LOH)) or epigenetic (promoter hypermethylation) changes." (PMID 23374397, 2013). "Compelling data have shown that breast tumors from patients carrying germline BRCA1/2 mutations are also morphologically and genetically different from each other as well as both sporadic and hereditary BRCAx-associated tumors." (PMID 23469205, 2013).
breast tumors (continued). "Further studies are needed to understand which additional factors contribute to make BRCA1 mutation carriers prone to the expression of different breast tumor phenotypes." (PMID 23374397, 2013). "The pathological features of breast tumors arising in BRCA1 mutation carriers have been extensively described." (PMID 23374397, 2013). "Several in vitro studies have indicated that breast tumor cells with BRCA1 mutations are extremely sensitive to drugs that induce cross links (mitomycin-C and platinum) and single- and double-strand breaks (etoposide and bleomycin) in DNA." (PMID 29147345, 2013). "BRCA1 deficient tumours exhibit characteristics similar to the basal-like subtype of breast tumours, which resemble the gene expression pattern of basal epithelial cells." (PMID 23863842, 2013). "It is interesting to note that, although CHEK2 interacts with BRCA1 in the same pathway, its mutations are significantly associated with estrogen receptor positive breast tumours, indicating an impact on tumour etiology that is different from BRCA1." (PMID 24025454, 2013). "For breast tissues, the only example of a cell-of-origin analysis for breast tumors has been extracted from the study of Brca1-deficient patients and mice." (PMID 23185480, 2012). "In summary, TBP tumors displayed heterogeneous histology, including high grade, central necrosis, metaplasia, pushing boarders, and metastasis, features that are characteristic of human BRCA1-mutated and Claudin-low breast tumors." (PMID 23173005, 2012). "Genetic analysis of the corresponding human homologs was performed in sporadic breast tumors and in inherited BRCA1-associated carcinomas." (PMID 22347400, 2012). "More studies are guaranteed to determine the role of miRNA more related to familial breast tumors and those specifically associated to the BRCA1 and BRCA2 mutated tumors." (PMID 22701724, 2012). "In previous work, we developed an aCGH-based classifier recognizing the genomic pattern of BRCA1-mutated breast tumours." (PMID 22032731, 2011). "To date, two BRCA2 deficient tumours, two BRCA1 deficient tumours, and two BRCA1 deficient cell lines have also been subjected to medium-depth whole genome sequencing, as part of a wider study of primary breast tumours and cell lines." (PMID 21750719, 2011). "Altered BRCA1 expression was significantly associated with high grade and poor prognosis breast tumours (p=0.006)." (PMID 23508738, 2011). "Both preclinical and clinical studies have found that BRCA1-associated breast tumors are sensitive to platinum agents and cyclophosphamide." (PMID 22295226, 2011). "We sought to test the value of selecting women for BRCA1 mutation testing on the basis of family history and/or breast tumour morphology criteria as well as the value of testing for large genomic alterations in BRCA1." (PMID 21281505, 2011). "BRCA1-linked breast tumours typically exhibit triple negative expression (ER-/PR-/Her2-), express basal cytokeratins 5 and 6, and EGFR and show similar histopathological features to basal-like/triple negative breast cancers." (PMID 21457545, 2011). "Breast tumors arising in BRCA1 mutation carriers are typically ER-negative, whereas most tumors in BRCA2 mutation carriers and sporadic cases are ER-positive." (PMID 22110403, 2011). "Sections from patients with various BRCA1 mutations, including M1775R and C64G (reported to have a similar defect in ubiquitin-ligase activity as the synthetic I26A mutation), and patients with normal BRCA1 breast tumors were examined." (PMID 21666281, 2011).
breast tumors (continued). "Of 156 breast tumours that stained with BRCA1, complete loss of nuclear expression was detected in 23 (15%) cases." (PMID 23508738, 2011). "The largest overlapping BRCA1-specific gain between mouse and human BRCA1-mutated breast tumors maps to human chromosome 1 and to mouse chromosome 6." (PMID 20735817, 2010). "Breast tumours arising in carriers of BRCA1 or BRCA2 mutations, however, also differ from one another and from sporadic tumours in terms of their pathological characteristics, including those assessed morphologically or by immunohistochemistry." (PMID 20482762, 2010). "Phenotypic features of BLBCs, such as clinical presentation and early age of onset, resemble those of breast tumors from BRCA1-mutation carriers." (PMID 21118481, 2010). "Metaplastic and medullary carcinomas both have a high incidence of methylation of BRCA1, and ~50% of breast tumors from BRCA1 mutation carriers show medullary-like features." (PMID 20813035, 2010). "BRCA1-mutated breast tumors are HR deficient (HRD) and can therefore be targeted with DNA-damaging agents or PARP inhibitors." (PMID 21118481, 2010). "BLBCs share molecular features that were previously found to be specific for BRCA1-mutated breast tumors." (PMID 21118481, 2010). "In line with this, and in contrast to most breast tumors, both BRCA1-mutated tumors and BLBCs often occur in premenopausal breast epithelia." (PMID 21118481, 2010). "Distinctive patterns of global gene expression have also been shown between breast tumors with BRCA1 mutations and breast tumors with BRCA2 mutations." (PMID 20174566, 2010). "We used this method to find CNAs that occur more often in BRCA1- or BRCA2-deficient breast tumors compared to BRCA-proficient control tumors." (PMID 20735817, 2010). "BRCA1-mutated tumors and BLBCs are both basal like TNBCs, characteristics that are different from hormone receptor positive luminal breast tumors." (PMID 21118481, 2010). "To allow direct comparison, we simultaneously performed immunohistochemistry for EZH2 on sections from luminal A, basal-like and BRCA1-mutated breast tumors." (PMID 19709408, 2009). "We have demonstrated using high-resolution genomic profiling coupled with analysis of tumour phenotypes that the development of a subset of sporadic breast tumours is similar to that of tumours derived from BRCA1- or BRCA2 germline mutation carriers." (PMID 19589159, 2009). "Breast tumors in BRCA1-mutation carriers arise early in life and exhibit an aggressive, basal-like phenotype associated with poor overall survival." (PMID 19709408, 2009). "This raises the question if not only BRCA1-deficient breast tumors but also sporadic basal-like tumors would be dependent on EZH2 overexpression." (PMID 19709408, 2009).
breast tumors (continued). "We now consider the identification of breast tumors that arose as the result of an inherited deleterious mutation of the BRCA1 gene." (PMID 19695104, 2009). "Consistent with our previous observation that EZH2 mRNA and protein levels correlate relatively well, we observed increased EZH2 protein levels in human BRCA1-deficient tumor sections compared with other breast tumors." (PMID 19709408, 2009). "Consistent with their basal-like characteristics, BRCA1-deficient breast tumors exhibit aggressive behavior and are associated with poor survival." (PMID 19709408, 2009). "For this purpose, we have used the Oncochip v2, a cancer-related cDNA microarray to analyze 14 BRCA1-associated breast tumours." (PMID 19826428, 2009). "BRCA1-associated breast tumours are mostly high-grade invasive ductal carcinomas (IDCs) that lack expression of estrogen receptor (ER), progesterone receptor (PR) and ERRB2/HER2, which is referred to as ‘triple-negative’ breast cancer." (PMID 19904273, 2009). "A distinct gene expression profile has been reported for breast tumors of BRCA1 mutation carriers, expected to be homozygous for loss of BRCA1 function at the somatic level." (PMID 18497862, 2008). "These mutations were made in the context of the BRCA1 L6 promoter, which extends from nucleotide -208 to +27 and which we have previously determined to have optimal promoter activity in human breast tumour lines." (PMID 17663789, 2007). "Because the majority of breast tumours in BRCA1 germline mutation carriers are of basal type, our observations are also relevant to the prognosis in these women." (PMID 17217540, 2007). "BRCA1 methylation has been shown to occur in sporadic breast tumours and to be associated with reduced gene expression." (PMID 16846527, 2006). "The strength of the method is exemplified by its application to a published gene expression data set of sporadic and familial breast tumors with BRCA1 or BRCA2 mutations." (PMID 16018805, 2005). "The expression profiles of 6 frozen breast tumour tissues with a proven BRCA1 gene mutation were weighed against those from 12 patients without a known family history but who had similar clinico-pathological characteristics." (PMID 11506493, 2001). "Using a high density membrane based array for screening of RNA isolated from these samples and standard algorithms and software, we were able to distinguish subgroups of sporadic cases and a group consisting mainly of BRCA1-mutated breast tumours." (PMID 11506493, 2001). "We carried out AI and fluorescence in situ hybridization (FISH) analyses of BRCA2 in breast tumours from germ-line BRCA1 mutation carriers and vice versa." (PMID 11710835, 2001). "Since Cezanne-deficiency leads to decreased BRCA1 levels, we reasoned that breast tumors with low expression of Cezanne may be associated with HR deficiency displaying “BRCAness” in tumors." (PMID 41359628, 2025). "It remains to be studied whether Cezannelow or Ube2Shigh tumors exhibit features similar to that of a subset of BRCA1-deficient ER+ breast tumors." (PMID 41359628, 2025). "To study mechanisms of PARPi resistance in-vivo, we isolated Brca1- or Bard1-deficient breast tumor cells (hereafter referred to as “Brca1-def” and “Bard1-def”) derived from Brca1- or Bard1-conditionally deleted mice and injected these cells in the mammary glands of syngeneic B6/129F1 mice." (PMID 38956205, 2024). "However, breast tumors in BRCA1 and BRCA2 mutation carriers generally show different histopathology." (PMID 38059556, 2024).